TRAJ57 (T cell receptor alpha joining 57)
Gene: T-cell receptor joining (J) gene on chromosome 14 (22,478,872 to 22,478,934, forward strand). Ensembl gene ENSG00000211834.
Diseases named in the same sentence as TRAJ57 in open-access papers:
TRAJ57 is named in the same sentence as 2 diseases in open-access papers, as found by Europe PMC text mining. Sharing a sentence is not in itself a finding about the gene and the disease.
TRAJ57 shares sentences with these, for which no sentence is quoted: metal (2 papers); Allergy (1).